ZEB1 (zinc finger E-box binding homeobox 1)
Diseases named in the same sentence as ZEB1 in open-access papers (continued):
Sharing a sentence is not in itself a finding about the gene and the disease.
cancer (continued). "Previous reports identified the PI3K-Akt pathway as an enhancer of the expression of epithelial and mesenchymal transition (EMT) resultant transcription factors such as Snail, Slug, ZEB1, and ZEB2 that promoted the EMT and resulted in an elevation of the cancer cell motility." (PMID 36009568, 2022). "Similarly, no significant expression changes were observed in the studied mesenchymal markers in the resistant cancer cells such CDH2, VIM, ZEB1, ZEB2, SLUG, TWIST1 that which are upregulated in completed EMT." (PMID 35523936, 2022). "Suppression of ZEB1 gene expression decreases cancer angiogenesis while eliciting continuous cancer vascular normalization." (PMID 36547923, 2022). "ZEB1 and ZEB2 may have multiple functions that will be elucidated by analyses of specific cancer types in the future." (PMID 35723302, 2022). "Furthermore, the silencing of STK25 decreased the transcript levels of Slug and Zeb1, which are the critical transcriptional factors regulating EMT of cancer cells." (PMID 34624527, 2022). "ZEB1 is a transcription factor that promotes epithelial-to-mesenchymal transition (EMT) by downregulating the epithelial marker E-cadherin, therefore facilitating cell motility and cancer dissemination." (PMID 36358805, 2022). "ZEB1/2 are positively correlated with EMT phenotypes and the aggressiveness of cancers." (PMID 35451213, 2022). "Among these ESE proteins, ESE1 and ESE3 suppressed ZEB1/2 expression in cancer cells, whereas ESE2 failed to perform this function." (PMID 36140527, 2022). "Studies have shown that Wnt/β-catenin signaling could upregulate the expression of Slug (Snai2), ZEB1, and ZEB2 in cancer cells, thereby reducing the level of E-cadherin to promote cell migration." (PMID 36398031, 2022). "The lncRNA ATB promotes the EMT of several types of cancer cells via sponging miR-200s, an EMT suppressor inhibiting ZEB1/2 expression via direct binding to their 3′UTR, which is detected between ATB and miR-200a/b/c in an RNA immunoprecipitation (RIP) experiment." (PMID 35736633, 2022). "For example, the expression of zinc finger E-box binding homeobox 1 (ZEB1), a lipogenic regulator promoting the inclusion of long-chain PUFAs into the cell membrane, was positively correlated with GPX4 sensitivity across 610 cancer cell lines." (PMID 35883577, 2022). "Here, we focus on the role of Zeb1, a well-characterized epithelial-to-mesenchymal transition (EMT) inducer which has been demonstrated to confer stem-cell-like characteristics in multiple cancer types in stemness regulation of HSCs." (PMID 36008379, 2022). "In this loop, miRs were shown to suppress EMT while ZEB1/2 promotes EMT and cancer progression." (PMID 33803458, 2021). "Cancer EMT is induced by EMT-promoting transcription factors such as Slug, Snail, ZEB1, and Twist." (PMID 33573293, 2021). "Zeb1, a zinc finger E-box binding homeobox epithelial-mesenchymal transition (EMT) transcription factor, confers properties of “stemness,” such as self-renewal, in cancer." (PMID 33108352, 2021). "ZEB1 is considered as a driver of EMT and cancer progression." (PMID 34539879, 2021). "Zinc finger E-box binding homeobox 1 (ZEB1), a core EMT-transcription factor, endows cancer cells with a mesenchymal-like and stem-like phenotype and correlates with poor clinical outcomes in human cancers." (PMID 34163033, 2021). "In cancer cells, EMT-induced signals may be the results of EMT-transcription factors, including ZEB1 and TWIST1." (PMID 34885101, 2021). "Of interest, ZEB1 and xCT were significantly overexpressed in GBM samples, whereas they were absent in the control brain sample, further highlighting their importance in the cancer landscape." (PMID 34885110, 2021).
cancer (continued). "ZEB1 is one of the most important drivers of EMT and cancer progression." (PMID 33897890, 2021). "These scores were also able to recapitulate in vitro observations that, while TGF-β treatment was able to induce EMT in MCF10A cells, the extent of EMT induced was decreased upon the knockdown of ZEB1 (GSE1248423), a key EMT-inducing transcription factor in many cancers." (PMID 35053177, 2021). "Thus, strategy that disrupts the regulatory effect of ZEB1 on PFKM should be developed as a treatment to HCC and other cancers with excessive expression of PFKM driven by ZEB1." (PMID 33897890, 2021). "In patients with advanced BCs in advanced stage (TNM III and IV), downregulated miR-203a-3p, and SNAI2 with ZEB1 were detected in TU-C and TU-IF, and upregulation of SNAI1 and miR-205-5p was found in samples with disseminated cancer cells, LNM and CD45-DB fractions, respectively." (PMID 35008529, 2021). "Interestingly, in TNBC cell lines, TENM2 seems to be regulated by the Zinc finger E-box binding homeobox 1 (ZEB1), a transcription regulator with a potential role in cancer progression that is involved in promoting the EMT." (PMID 33652578, 2021). "The fact that Zeb1 affects cell survival and proliferation of all pancreas lineages is in agreement with its capacity to completely reprogram cells during EMT in cancer, leading to ample changes in cellular properties including metabolism and cell architecture." (PMID 34112759, 2021). "Moreover, FBXO45 inhibited cancer development and metastasis by targeting EMT-inducing transcription factors, including SNAI1/2, TWIST1/2, and ZEB1/2, in various cancer cells." (PMID 33966034, 2021). "In agreement with previous studies, we showed that ERK–ZEB1 signaling promotes epithelial to mesenchymal transition in cancer cells, and treatment of CD44-overexpressing cells with ERK phosphorylation inhibitor PD98059 reversed ZEB1 and Claudin-1 expression levels." (PMID 34439211, 2021). "Furthermore, protein expressions of the ZEB1 and ZEB2 transcription factors, which are targets of hsa-miR-200c-3p and play key roles in cancer cell migration and invasion, were significantly enhanced in these cells." (PMID 34573283, 2021). "One strategy might be to target ZEB1, given that ZEB1 is an essential driver of EMT activation and metastasis in cancer." (PMID 34210327, 2021). "As one of the most important EMT-inducing transcription factors, ZEB1 not only transcriptionally represses but also activates some EMT-related genes, and its overexpression promotes tumorigenesis and metastasis in human carcinomas." (PMID 34409034, 2021). "MiR-139-5p was confirmed to negatively regulate ZEB1 and ZEB2 expression 31, which induces EMT and promotes the progression of malignant carcinoma 54, while overexpression of ZEB1 and ZEB2 abolishes the inhibitory effects of miR-139-5p on HCC cell migration and invasion." (PMID 34522182, 2021). "Notably, the survival analysis indicated that cancer patients with concomitantly high expression of p-RB, p-USP51, and ZEB1 in their tumors had shorter overall survival than those with low p-RB, p-USP51, and ZEB1 expression." (PMID 32296027, 2020). "ZEB1 engages in a feedback loop with TGF-β and miR, thereby promoting metastasis of cancer cells." (PMID 32664703, 2020). "Notably, ZEB1 and miR-200s have the opposite functions to regulate EMT and the characteristics of cancer cells but also reciprocally control the expression of each other, which is a double-negative feedback loop named the ZEB1/miR200 feedback loop." (PMID 32014049, 2020). "It is also vital to explore the relevance of ZEB1 and ZEB2 proteins in cancer therapy." (PMID 32664703, 2020). "These miRNAs exhibit tumor suppressor activity to antagonize EMT associated with cancer metastasis by silencing E-cadherin, such as ZEB1 and ZEB2 in various cancers such as colorectal cancer, gastric cancer, pancreatic cancer, ovarian cancer, and nasopharyngeal cancer." (PMID 33007962, 2020).
cancer (continued). "Furthermore, SFN can inhibit epithelial-to-mesenchymal transition (EMT)—an important mediator of cancer cell invasion and metastasis—via regulation of COX-2/matrix metalloproteinase (MMP)-2, -9/ZEB1, Snail, and miR-200c/ZEB1 in BC cells." (PMID 32013065, 2020). "We found that the knockdown of USP51 resulted in significantly decreased lung metastasis; however, this effect was attenuated in mice carrying ZEB1-expressing tumors, confirming that the knockdown of USP51 reduces cancer metastasis through the regulation of ZEB1 in vivo." (PMID 32296027, 2020). "ZEB1, a member of ZEB family, has key roles in EMT, migration and invasion in human cancers." (PMID 32862492, 2020). "Zinc finger E-box binding homeobox 1 (ZEB1) is a prime element of a network of transcription factors controlling EMT and has been identified as an important molecule in the regulation of DNA damage, cancer cell differentiation, and metastasis." (PMID 32266287, 2020). "Additionally, zinc finger E-box binding homeobox 1 (ZEB1) is an upstream mediator of EMT and contributes to the metastasis and invasion of cancer cells via the induction of EMT." (PMID 32784981, 2020). "We examined the expression of P-STAT3 and ZEB1 in cancer tissues and noncancerous tissues and found that the expression of ZEB1 in HNSCC tissue was significantly upregulated, while STAT3 was significantly phosphorylated." (PMID 33363013, 2020). "By STRING, it was shown that ZEB1 can also directly bind to a variety of proteins (e.g., STAT3 and TWIST) regulating cell adhesion, migration and epithelial cell proliferation, and work together on cancer occurrence and progression." (PMID 33392180, 2020). "This once again highlights that onco-suppressor miRs may suppress ZEB1 via affecting other EMT-TFs such as TGF-β, and that ZEB1 can form a negative feedback loop with onco-suppressor miRs in promoting metastasis of cancer cells." (PMID 32664703, 2020). "Additionally, YAP interacts with EMT-induced transcription factors ZEB1, SNAIL, and SLUG, and their complex promotes cancer stem cell (CSC) traits." (PMID 32252322, 2020). "Additionally, through targeting the miR-429/ZEB1 axis, XIST also affects morphology of cancer cells, such that silencing XIST results in a change in cell morphology, from the original spindle shape to a rounded one." (PMID 32664703, 2020). "ZEB1 and UBQLN1 have been found to regulate each other in order to induce EMT in cancer cells." (PMID 32549375, 2020). "ZEB1 is a critical activator of EMT in thyroid and other cancer types." (PMID 32157211, 2020). "Under normoxic conditions, cancer cells showed focal or absent Zeb1 expression, without significant SK3 staining." (PMID 32640738, 2020). "Furthermore, there was an autocrine feedback loops among ESRP1, HAS2, CD44, and ZEB1 in the aberrant activation of EMT, which acted in the dynamics of EMT in cancer metastasis." (PMID 32211324, 2020). "ZEB gene family (zinc finger E-box binding homeobox) comprises two major members, ZEB1 and ZEB2, that are transcriptional repressors and epigenetically modulate the expression of CDH1 in multiple human cancers." (PMID 32987716, 2020). "ZEB1/2 expression in epithelial cells results in EMT and a mesenchymal phenotype, promoting invasion, metastatic dissemination and de-differentiation to a cancer stem cell state." (PMID 32318352, 2020). "Various EMT transcription factors have been proposed among different cancer types, including Snail, Slug, TWIST1/2, and zinc finger E-box-binding homeobox 1/2 (ZEB1/2), as they may affect transcription of E-cadherin and other EMT markers." (PMID 31963305, 2020). "ZEB1 plays pivotal roles in the induction of EMT and cancer metastasis, which led us to examine whether CDK4/6 inhibition could regulate cancer metastasis via ZEB1." (PMID 32296027, 2020).
cancer (continued). "Several studies have demonstrated the link between EMT and stemness in a variety of human carcinoma, and recently, EMT with its mediators, such as Zeb1, Snail, Slug, and NF-kB, has been described as a key mechanism by which cells are conferred with stem-cell properties." (PMID 32803272, 2020). "Among all PMFs, tangeretin was the most effective in targeting cancer stemness and self-renewal ability, whereas scutellarein tetramethylether was shown to modulate EMT-related markers (increasing CDH1 and reducing ZEB1 and SNAI1 expression) and highly synergistically interact with 5-FU." (PMID 30717428, 2019). "Indeed, the fatostatin treatment led to decreased SREBP1 expression as well as vimentin, ZEB1, and metastatic potential of both OE21 and OE33 cancer cells." (PMID 31861383, 2019). "Moreover, expression of canonical EMT-inducing transcription factors such as Snail1/2, Slug, ZEB1 (Zinc Finger E-box-binding Homeobox 1) and Twist is driven by YAP in a variety of cancers." (PMID 32118029, 2019). "Although Zeb1 has been well demonstrated to induce the EMT of cancer cells, including CRC cells, by inhibiting E-Cad, the role of Zeb1 in the RP11-induced dissemination of CRC cells was unknown and thus investigated." (PMID 30979372, 2019). "Therefore, crosstalk between YAP/TAZ and EMT transcription factors such as ZEB1/2, Snail/Slug, and Twist modulates the EMT programs, thereby acquiring the characteristics of malignant cancer cells." (PMID 31100975, 2019). "Similarly, lncRNAs ZEB1 antisense 1 (ZEB1-AS1) and ZEB2 natural antisense transcript (ZEB2-NAT) promote the expression of ZEB1 and ZEB2, respectively, leading to increased metastasis and poor prognosis in numerous types of cancer." (PMID 30791369, 2019). "Zeb1 has been shown to induce EMT in PCa cell lines and promote cancer cell migration and invasion." (PMID 31752242, 2019). "As EMT phenotype of chemoresistant cancer cells has been documented, it is not surprising that the mRNA and protein expression levels of Snail, Slug, ZEB1, Vimentin, and Fibronectin were higher in GR cells compared with parental cells." (PMID 31783584, 2019). "PFD treatment reduced cancer cell migration and invasion by reducing the Integrin α6 and uPAR levels and suppression of the expression of epithelial-to-mesenchymal transition (EMT) factors, vimentin and Zeb1." (PMID 31492002, 2019). "Third, UCA1 overexpression could promote cancer metastasis by activation of metastasis-related genes including GRK2/ERK-MMP9, EZH2/AKT, p21/E-cadherin, iASPP, KLF4-KRT6/13, FGFR1/ERK and ZEB1/2-FSCN1." (PMID 30918102, 2019). "Emerging evidence has demonstrated that several miRNAs could target the 3ʹ-UTR of the ZEB1, a key transcription factor of EMT, and post-transcriptionally regulate its expression in cancers." (PMID 31092700, 2019). "Additionally, as a transcription factor, SIX1 enhances VEGF-C and ZEB1 expression to promote EMT, invasion and metastasis of cancer cells." (PMID 31438963, 2019). "Thus, by Western blot and immunoblot analysis, it was reported in CRC samples a positive correlation between IL-13Rα1 and ZEB1 probably demonstrating that IL-13/IL-13Rα1/STAT6/ZEB1 axes promote EMT and aggressiveness of this cancer." (PMID 31781477, 2019). "ZEB1 exhibited a modest positive correlation with cancer cell antigen presentation and was not correlated with cancer cell recognition by immune cells." (PMID 31780722, 2019). "ZEB1 is known as a transcriptional repressor of epithelial genes; however, a recent paper by Lehmann has reported that ZEB1 switches its function to a transcriptional co-activator by interacting with YAP1 in aggressive cancers." (PMID 30909436, 2019).
cancer (continued). "Carcinoma cells admixed with CAFs showed stronger E-cad, vimentin, and fibronectin staining as well as nuclear ZEB1 staining than did those comingled with/without control fibroblasts." (PMID 31331982, 2019). "The reduced level of Zeb1 in the cancer cells is not sufficient to maintain repression of E-cadherin, and EMT is reversed." (PMID 29930325, 2018). "ZEB1 may thus function as an oncogene that maintains a balance to allow cancer cells to proliferate in the presence of genome instability that serves as a source of cancer-promoting mutations, without accumulation of excessive DNA damage that leads to proliferative arrest or apoptosis." (PMID 29352223, 2018). "ZEB1 even under normal conditions can be very complex with opposing functional activities so it is not unreasonable to believe that in cancer the complexity of ZEB1 would remain, and in fact be greater due to ZEB1 dysregulation." (PMID 32309604, 2018). "Moreover, overexpression of Snail enhances expression of ZEB1, another key molecule for EMT induction, and in turn promotes the aggressiveness of cancer cells." (PMID 29969465, 2018). "This is especially compelling because even small reductions of Zeb1 levels could have considerable impact in preventing EMT and curtailing metastasis, which in turn could have a profound impact in reducing cancer progression and mortality." (PMID 30405106, 2018). "In development and cancer, Snai1 expression typically precedes and helps induce the expression of other EMT TFs including Zeb159–61, and thus it is interesting that in our system Zeb1 can induce Snai1, perhaps through indirect mechanisms." (PMID 30405106, 2018). "Cancer database and molecular analyses revealed that it activates Wnt/β-catenin signaling axis, as evident by enhanced nuclear localization and function of β-catenin marked by increased level of SNAIL1, SNAIL2, ZEB1, and TWIST1 and its downstream gene targets." (PMID 29748568, 2018). "But, this induction of Zeb1 does not restore a CD44hi CGC-like population among the invading cancer cells." (PMID 29930325, 2018). "Additionally, the expression of ZEB1 in ESCC tissues and corresponding non-carcinoma tissues was determined by qRT-PCR." (PMID 29416674, 2018). "Thus, ZEB1 is best known as a transcriptional repressor of CDH1 and inducer of EMT in breast and other carcinomas." (PMID 29744893, 2018). "The results revealed that ZEB1 expression was relatively lower, while NGN3 expression was higher in low-grade tumors, a result consistent with findings from a previous report showing that cancer stem cells are enriched in high-grade tumors." (PMID 28903350, 2017). "Twist1 and Zeb1 immunohistochemistry was performed using FFPE tissues of PTC, but no increase in the expression of Twist1 and Zeb1 at the invasive border was observed as compared with the corresponding cancer centre." (PMID 28489070, 2017). "While expression of ZEB1 and ZEB2 is suppressed by epithelial miR‐200 family of miRNA, TGF‐β induces their expression in addition to some other EMT‐related transcription factors, including Snail, and Slug, in certain types of normal and cancer cells." (PMID 28618162, 2017). "Though double-negative feedback loop between the miR-200 family and ZEB1/2 remains to be the most widely existed in many types of cancer, it has also been applied in many other miRNAs such as miR-203 and miR-145." (PMID 27992370, 2017). "EMT and the mesenchymal epithelial reverse transition (MErT) are complex processes involved in normal development and diseases such as cancer and fibrosis that are driven by EMT regulators (SLUG, ZEB1, TWIST and others) and miRNAs together with epigenetic regulators." (PMID 28415643, 2017). "Mucin 1 (MUC1) and WNT1 inducible signaling pathway protein 1 (WISP1) have been reported to inhibit E-cadherin-mediated cell-cell adhesion, induce the expression of transcription factors (Snail, N-cadherin, ZEB1 and Smad2), and in turn activate EMT in cancer cells." (PMID 28099903, 2017).